CD4 (CD4 molecule)
Diseases named in the same sentence as CD4 in open-access papers (continued):
Sharing a sentence is not in itself a finding about the gene and the disease.
infection (continued). "Especially, CD4+ T cells are activated and differentiated into Th1/Th17, help the development of memory T cells, and then recruited to the gut to fight against the infection of bacteria, fungi, and viruses." (PMID 32724827, 2020). "(C) GFP levels (mean fluorescence intensity (MFI), gated on infected cells) in primary CD4+ cells from four donors after infection with V1/δ-Vpr or V1/HA-Vpr." (PMID 32538781, 2020). "It was possibly because of the shorter follow-up time of these individuals from the cohort, as individuals with double infection initiated ART at higher CD4+ T-cell counts." (PMID 32038599, 2020). "Studies in animal models of OPC have demonstrated that CD4+ Th17 cells are involved in the control of infection." (PMID 32185141, 2020). "In the murine model, resistance to infection depends on the host immunity mediated by CD4 T-cell cytokines and macrophages." (PMID 32477357, 2020). "This suggests that a SARS-CoV-2 vaccine candidate consisting of S protein can induce a robust CD4+ T cell response that recapitulates the elicited immune response during the natural infection." (PMID 33193454, 2020). "In this well-established experimental model, infection of BALB/c mice with L. major induces a Th2 immune response characterized by high levels of CD4+ Th2 cells producing IL-4 and low levels of CD4+ IFN-γ+ Th1 cells." (PMID 33212818, 2020). "Batf3−/− naive recipient mice received either CD4 or CD8 T cells from Batf3−/− naive or infected mice 1 day before infection with RHΔku80Δrop5 parasites and were monitored for 30 days." (PMID 32669460, 2020). "Similar to HIV-1, FIV infection results in an acute phase with minor symptoms, an inconstant latent phase and detrimental CD4+ T-cell depletion." (PMID 32650790, 2020). "This phenotype facilitates the infection of macrophages that express a low density of CD4 on their surface." (PMID 32992787, 2020). "At 14 days while CD4+ T lymphocytes had the same values as the pre-infection, CD8+ T lymphocytes were still −13.6% compared to 0 dpi." (PMID 33178728, 2020). "On the contrary, an increase in the total quantity of cell-associated SIV DNA was observed from the acute to the initial steady state phase of infection in peripheral LNs, mostly driven by the increased number of CD4 T cells." (PMID 31723251, 2020). "Upon infection, M. tuberculosis-specific CD4 T cells expressing KLRG1 exhibited a heightened capacity to secrete IFN-γ." (PMID 33193338, 2020). "It was noteworthy to observe maintained CD4+ TN compartment in VNPs despite an extended duration of infection with a high viral replication." (PMID 32194543, 2020). "While mRNA expression of PD-1 was detected increased at the early cytolytic phase of infection or on CD4+ T cells of SPF birds at 21 dpi, PD-L1 expression increases at the latent phase." (PMID 32080753, 2020). "Reported in the literature, CD4 T lymphocyte count< 200/ul and viral load> 500,000 copies/ul, the incidence of postoperative incision infection wound would increase." (PMID 33243159, 2020). "Yet, how the activation of innate immune responses in DCs and macrophages influences the likelihood of CD4+ T cell infection and subsequent spread of virus remains elusive." (PMID 31968566, 2020). "The kinetic of all the viral transcripts generated during infection of CD4+ T cells from donor 4 was then assessed by ONT sequencing." (PMID 32807178, 2020). "Yet, dissecting age and infectious history of the patients revealed that while CD8+ T-cell differentiation seems to be triggered by development, CD4+ T-cell functionality is partly impaired by infections." (PMID 32849561, 2020). "To further ascertain the molecular response during the infection of C. sinensis, we measured the CD4+T cell subsets-related cytokines, including IL-10, IL-17, IL-4, IL-2, and TNF-α by ELISA methods." (PMID 33489026, 2020).
infection (continued). "We followed trans-infection through co-culture of iMDDCs with CD4+ T lymphocytes, in the presence of CXCR4-tropic replicative-competent HIV-1 expressing GFP." (PMID 32181159, 2020). "Inflammasome activation by NOD-like receptors is also a major mechanism of pyroptotic CD4+T cell depletion due to HIV in ex vivo models of infection." (PMID 32582566, 2020). "From the perspective of immunosenescence, here we described the changes of CD4+ T lymphocyte subpopulations and their correlation with infection and chronic inflammation." (PMID 33269101, 2020). "It was described that Nef alone was transported from macrophages to T cells via TNT, a process that resulted in a decrease of CD4 expression in recipient T cells, and thus limiting cell-free infection events in these cells." (PMID 32354203, 2020). "Given that C-HIV is the most prevalent subtype of HIV-1 globally, we sought to determine the cellular tropism of C-HIV Envs sampled from the first 3 years of untreated infection for different memory CD4+ T cell subsets." (PMID 32762760, 2020). "CD4 T helper cells, as a key component of this system, play a critical role in defending infections throughout life by coordinating the actions of other immune cells as well as non-immune cells." (PMID 33126494, 2020). "It is possible that naïve antigen-specific CD4+ T cells play a previously unappreciated role in responding to C. trachomatis following secondary infection." (PMID 33091023, 2020). "As a group, the HLA-B*57:01-positive patients showed initially higher CD4 T-cell counts, which were similar after 3 years of infection." (PMID 32350076, 2020). "Even though there was a balance of IFNγ and IL-17 producers in the CD4+ compartment as needed to effectively fight infections, frequencies of Th17 cells clearly dropped in half by patients suffering from upper airway inflammations (group 2)." (PMID 32849561, 2020). "Early studies using NHP models demonstrated that antibodies and CD4 T cells are necessary for rVSV-EBOV-mediated protection against lethal infection while CD8 T cells play a minor role." (PMID 32992829, 2020). "After the infection with T. cruzi, interleukin-17A (IL-17A) is produced by T helper 17 (Th17) cells, subset of CD4+ T cells, and innate lymphoid cells." (PMID 32193469, 2020). "It is likely that the efficient interplay between helper CD4 T cells and B cells to promote the production of high-affinity and potently neutralizing antibodies is essential for inducing post-infection immunity." (PMID 33262993, 2020). "In L. donovani infected C57BL/6 mice, the frequency of splenic IFN-γ+ IL-10+ T-bet+ CD4+ T cells is increased on day 28 post-infection." (PMID 32849534, 2020). "More than five weeks after infection, we detected persistent pneumonia with increased activated CD4+ and CD8+ lymphocytes as well as dendritic cells and MHCII expressing macrophages in the lung." (PMID 33260910, 2020). "We initiated the T cell characterization by comparing the FDS of CD4 T cells specific for the five different antigens following natural infection with Mtb." (PMID 33240275, 2020). "The effectors of Salmonella pathogenicity island - 2 (SPI-2) have been reported to suppress migration of dendritic cells to the site of infection, downregulate CD4 and CD8 T cell responses and polarize macrophage functions." (PMID 32269573, 2020). "Our results show the induction of STM-specific multifunctional CD4+ T cells after vaccination and infection with STM that predominantly possessed an effector memory phenotype and dominated in the porcine intestine." (PMID 33584671, 2020). "Of note, HA present on the surface of CD44-expressing CD4+ T cells prevents direct binding and infection of CD44-containing HIV-1." (PMID 32752131, 2020). "Although the use of primary MDDCs and CD4+ T cells is a representative model of HIV-1 trans-infection, employing methods such as siRNA transfection within established MDDCs has its limitations." (PMID 32075937, 2020).
infection (continued). "Few mutations outside of the CD4-contacting helix (sites 54–74), the N611 glycan motif, and N/CHR regions were selected for during either 293Trhm or 293Thu infection." (PMID 32098152, 2020). "This form of transmission mediates the spread of HIV from macrophages to CD4+ T cells, which is much more efficient than infection of CD4+ T cells by cell free virus." (PMID 32726944, 2020). "Our results demonstrate that upon recall, Ag-specific CD4+ T cells expand and then contract more quickly than during a primary infection." (PMID 32983171, 2020). "Data from the infection experiments were further corroborated by the expression of Vpu-S52,56D in HeLa-CD4/CXCR4/CCR5 cells." (PMID 32127461, 2020). "Immunity to T. gondii infection depends on IL-12 for the production of gamma interferon (IFN-γ) by NK cells early after infection, and by CD4 and CD8 T cells at later times." (PMID 32669460, 2020). "Initially, spleens were harvested from naïve mice and mice at 7, 14, and 28 days post-infection to document the expansion, contraction, and establishment of memory 2W1S-specific CD4 T cells." (PMID 32903436, 2020). "Enhanced effective CD4+ Th cell response has been clearly illustrated in human infection and experimental schistosome models, which is initiated as a Th1 response before abundant oviposition by female worms." (PMID 32197642, 2020). "Target cells were pre-treated with 66nM FTY720 for 48 hours (the concentration used in cell-to-cell infection experiments), then labeled with Cell Trace Yellow dye immediately prior to co-culture with infected CD4 T cells." (PMID 32790802, 2020). "B cells perform a vital function in combating infection through the production of antibodies and cytokines and antigen presentation to CD4+ and CD8+ T cells." (PMID 33302987, 2020). "It has been previously demonstrated that soluble CD4 protein is able to inhibit infection, suggesting that virus particles bound to the surface of the MDDCs were the main source of trans-infection." (PMID 32075937, 2020). "Consistent with single-dose infection models there is an essential role for CD4+ T cells in immunity during trickle infection." (PMID 32655568, 2020). "Here, the MR1 tetramer-defined MAIT cell population showed a significant decline in the CD4+ subset among total MAIT cells from pre-infection to the early chronic time point (p = 0.003; Friedman test with the Dunn’s multiple comparison test)." (PMID 31937782, 2020). "In all respective post-infection terms, both populations of T lymphocytes (CD4+ and CD8+) significant strongly responded to antigen stimulation with their early and late proliferation in E. cuniculi infected rabbits." (PMID 32539803, 2020). "In contrast, frequency and total number of CD4+ T cells increased significantly in the footpad following infection, compared to CD8 + T cells, indicating a possible role of those cells in the immune response during CBM." (PMID 32542003, 2020). "Infection with influenza viruses initiates virus-specific cellular immune response involving CD4+ T and CD8+ T cells." (PMID 32784697, 2020). "Using these reagents, we have previously uncovered aspects of the antigen-specific CD4+ T cell response that generate protective immunity during primary infection, including chemokine receptors required for T cell homing to the tissue and host sensing of IFNγ." (PMID 33091023, 2020). "In rickettsial infections, it is assumed that antibodies play a minor role in defense in primary infection because specific high-affinity antibodies that are produced with the help of CD4+ T cells are generated quite late in the infection." (PMID 33091016, 2020). "This scenario is supported by the observation that the infection of resting memory CD4+ T cells likely stems from an infection event during an activated state prior to the transition to a quiescent state, thus escaping elimination." (PMID 32970634, 2020).
infection (continued). "With the tools available for tracking antigen-specific T cell populations in this infection, Lm has been a central model for studying CD4+ T cell immunity in murine models." (PMID 32983171, 2020). "Surprisingly, individuals that remained uninfected had higher levels of CD161+ CD4+ T cells within the total T cell compartment, compared to pre-infection levels in individuals that eventually acquired HIV." (PMID 33322496, 2020). "We find that endometrial CD4+ T cells undergo unusually high levels of productive infection with R5-tropic HIV-1, likely reflecting in part the high expression of the CCR5 co-receptor on these cells." (PMID 32452381, 2020). "After infection, these cells were cultured under neutral conditions for three additional days, and then based on the simultaneous expression of CD4 and GFP by the retrovirus infection, the cells were sorted by flow cytometry." (PMID 32655569, 2020). "Our results showed that PLWHA with CD4+ T-cell counts below 200 cells/mm3 had a higher TM infection prevalence than those with CD4+ T-cell counts≥200 cells/mm3 (OR 12.68, 95%CI: 9.58–16.77)." (PMID 32727383, 2020). "Experimental CD4 depletion in SIV-infected rhesus macaques has been shown to result in productive infection of macrophages and microglia, with peripheral set point viral loads reaching levels two logs higher than undepleted controls." (PMID 32388691, 2020). "After ART interruption, we monitored rebound infection by measuring viral load, Gag-specific T cell response, Env-specific T cell response and CD4+ T cell count." (PMID 32130229, 2020). "HIV controllers exhibit more robust HIV-specific CD4 T cell responses compared to individuals with progressive, untreated infection." (PMID 32462053, 2020). "This reservoir is established as a result of direct infection of quiescent naive or memory CD4+ T cells; infection of CD4+ T cells differentially activated; and the transition of infected, activated CD4+ T cells to a resting memory phenotype." (PMID 33053801, 2020). "Binding of HIV gp120 to MR is further enhanced by oligomerization of the receptor on macrophages and dendritic cells, further promoting trans-infection of CD4+T lymphocytes." (PMID 32582566, 2020). "Estradiol is connected with CD4+ T cell numbers and increases T-reg cell populations, affecting immune responses to infection." (PMID 32490931, 2020). "Mice with NK depletion displayed significantly lower frequencies of IFN-γ+ CD4+ or CD8+ T cells but a higher percentage of IL-4+ CD4+ T cells compared to control mice in both spleen and lung tissues at day 3 after secondary infection." (PMID 32626664, 2020). "In other studies using C57BL/6 mice, we detected much greater numbers of TB10.4-specific CD8+ T cells than ESAT-6-specific CD4+ T cells in both the lung and draining lymph nodes during the first month following aerosol infection." (PMID 32673357, 2020). "In resting primary CD4+ T-cells, we follow the fate of the provirus starting at infection until latency is firmly established." (PMID 31999790, 2020). "Then, to determine the diversity of the TCRVβ+ repertoire in the site of the infection, the expression of each different TCRVβ+ by CD4+ and CD8+ T cells in the spleen and lungs for all experimental groups is shown as pie charts." (PMID 32093256, 2020). "To determine how oral mucosal Tregs contribute to immune cell changes during infection, we analyzed the CD4+T cell response in CLN and MOIL in MFYcre mice infected with CA." (PMID 33240286, 2020). "Seven days after infection, IL-22 deficiency also culminated in a reduction in IFN-γ or IL-17-producing CD4+ T cells in the lungs." (PMID 32517114, 2020). "Upon infection, the migration of dendritic cells (DCs) from the lungs to the draining lymph nodes was induced, resulting in the activation of CD4+ T cells." (PMID 32784697, 2020).
infection (continued). "PD-1 expression was also significantly decreased on CD4+ T cells, however, only during early stages of infection, while the PD-1 expression on regulatory T cells remained unchanged over the course of chronic infection." (PMID 32152316, 2020). "The presence of Gag-positive cells by flow cytometry was used as an indirect measure of infection of CD4+ T cells." (PMID 32066770, 2020). "Virus-specific CD4+ T cells detected at 2 years after infection in recovered individuals exhibited central memory while CD8+ T cells effector memory phenotypes, and CD8+ T cells produced high levels of IFN-γ and TNF-α upon peptide stimulation." (PMID 33062077, 2020). "The lower frequencies of multiple important CD4+ T cell subsets and increased exhaustion that we observed in multivariant infection are consistent with faster depletion of CD4+ T cells." (PMID 32886726, 2020). "Early cytolytic infection occurs primarily in B cells 3–6 days post-infection, and latency is established 7–10 days post-infection in activated CD4+ T lymphocytes." (PMID 33212952, 2020). "To evaluate the role of antigen-specific CD4+ T cells in vaccine-induced protection, we depleted CD4+ T cells prior to infection." (PMID 32817694, 2020). "In the presence of this sub-clinical infection a population of long-lived effector CD4 T cells that express CD44 and IL7R exist." (PMID 32244916, 2020). "HIV destroys these CD4 cells, weakening a person’s immunity against infections such as tuberculosis and some cancers." (PMID 32874668, 2020). "We expected the blood T cell repertoires of uninfected mice (containing both CD8 and CD4, sampled 7 days before infection) to contain much higher levels of clonal diversity than that observed in the spleen/LN and lung repertoires." (PMID 32547546, 2020). "Notable exceptions include several CD4+ T cell-associated genes (including HPGDS and MYD88), which were transiently upregulated during the ramp-up and peak stages of infection." (PMID 32119719, 2020). "In mouse models of infection, both CD4+ T cells and γδ T cells produce cytokines and protect against SA." (PMID 33312179, 2020). "HIV-infected CD4 T cells exhibited an initial increase followed by a gradual decrease in telomere length after infection." (PMID 33643305, 2020). "As such ILC3 were reported to be a critical source of protective IL-22 early during infection with Citrobacter rodentium, and depletion of CD4+ CCR6+ ILC3 using an anti-CD4 antibody led to diminished IL-22 production and enhanced bacterial tissue infiltration." (PMID 33603753, 2020). "We found that TIGIT is indeed highly expressed during the course of chronic LCMV clone 13 infection on both CD4+ and CD8+ T cells as well as on Tregs, the latter displaying the highest expression of TIGIT throughout the course of infection." (PMID 32152316, 2020). "Recently, a ratio based on CD27 median fluorescent intensity (MFI) on CD4+ T-cells compared to that on IFN-γ+CD4+ T-cells has been shown to differentiate active disease from infection." (PMID 32131556, 2020). "Previous studies from our lab have demonstrated robust epitope-specific CD4+ T cell activation during ECTV infection, suggesting that blockade of direct endogenous MHCII presentation is bypassed in some way." (PMID 32745153, 2020). "After infection, IL-2+ CD4+ T cells or TCM cells were still dominated in the lung of all vaccinated groups." (PMID 33117374, 2020). "Sham or CLP surgery was performed on the remaining mice 30 days post-infection, and the number of total and 2W1S-specific CD4 T cells in the spleen were determined 2, 7, 14, and 28 days post-surgery by flow cytometry." (PMID 32903436, 2020). "Salmonella-2W1S infection stimulates a robust Ag-specific CD4 T cell response because the bacteria replicate in the phagosomes of dendritic cells and macrophages—the location of peptide:MHC II complex formation." (PMID 32903436, 2020).